INS (insulin)
Diseases named in the same sentence as INS in open-access papers (continued):
Sharing a sentence is not in itself a finding about the gene and the disease.
diabetes (continued). "The combined risk factors reported to be associated with PAH include systemic hypertension, diabetes, uric acid level, age, insulin status, obesity, thyroid problems, and female sex hormones." (PMID 35457576, 2022). "Two possible mechanisms have been proposed for the importance of insulin clearance for diabetes risk: in one concept, insulin resistance per se leads to reduced clearance and diabetes risk." (PMID 35163746, 2022). "Several studies also examined the association of diabetes diagnostic markers or GDM with milk insulin, but these results were inconsistent across studies and currently provide limited evidence." (PMID 35277026, 2022). "While glucagon is primarily released from α-cells, which enhance insulin secretion, the role of glucagon and α-cells and their associations with proinsulin levels in diabetes progression need to be evaluated in future studies." (PMID 35887628, 2022). "Diabetes mellitus is a type of metabolic disease characterized by hyperglycemia, primarily caused by defects in insulin secretion, insulin action, or both." (PMID 36339446, 2022). "Diabetes are associated with a relative or absolute insufficiency of insulin, or insulin resistance, which results in metabolic disturbance of carbohydrates, lipids, and proteins." (PMID 36219347, 2022). "In conclusion, the insulin data in rodent models of type 1 diabetes suggest that diabetes-associated LUT function can be mostly or partially reversed." (PMID 35545721, 2022). "The mechanism underlying decreased retinal vessel density after insulin intensification in patients with type 2 diabetes mellitus is unclear." (PMID 35459162, 2022). "Diabetes is another complex chronic disease; diabetes is a metabolic disorder that manifests as hyperglycemia caused by insufficient insulin secretion." (PMID 35214519, 2022). "Diabetes mellitus is a metabolic disorder characterized by high-blood glucose levels caused by deficiencies in insulin secretion or insulin action resistance." (PMID 36466089, 2022). "For instance, in populations of Middle Eastern and Asian ethnicity, insulin deficient diabetes is more prevalent whereas in African populations insulin resistant diabetes is more common than in European populations." (PMID 36247141, 2022). "Chronic deregulation of glucose and lipid metabolism is a consequence of the impaired and insufficient secretion of insulin associated with beta-cell failure, which are the main remarks of type 2 diabetes mellitus (T2DM)." (PMID 36341058, 2022). "Diabetes mellitus is a metabolic disease with hyperglycemia caused by defective insulin secretion, defective insulin action, or both." (PMID 36699684, 2022). "There is research suggesting that CFTR loss-of-function drives impaired insulin secretion; however, there is also evidence that the resultant diabetes occurs solely as a consequence of pancreatic inflammation." (PMID 35769082, 2022). "Diabetes occurs in two types: type 1 diabetes results from the inability of the islets to secrete insulin, and in most instances, it is attributed to genetic causes and is hereditary." (PMID 35747025, 2022). "Studies in diabetic mice show the role of circulating ACE2 in improved parameters of glycemia through direct effects on the pancreas, improving insulin sensitivity and glucose-mediated insulin release, and a reduced risk of developing diabetes." (PMID 35448480, 2022). "In infants followed from birth, anti-insulin antibodies were detected early in the diabetes process in at risk subjects." (PMID 35498419, 2022). "CFRD has characteristics of both type 1 and type 2 diabetes mellitus, as it is caused by both a quantitative deficiency of insulin and the development of peripheral resistance to the hormone’s action." (PMID 35887806, 2022). "Type 1 diabetes mellitus (T1DM) results from a deficiency of insulin secretion and has genetic and autoimmune risk factors." (PMID 35204128, 2022).
diabetes (continued). "Diabetes mellitus is a chronic metabolic disease characterized by hyperglycemia, usually caused by insufficient insulin secretion or impaired insulin action, accompanied by disorders in the metabolism of three major nutrients: sugar, fat, and protein." (PMID 35164115, 2022). "DIo is a measurement of β-cell function adjusted for insulin sensitivity, and the decline in β-cell function appears in high-risk individuals years before the development of overt diabetes." (PMID 36247141, 2022). "Diabetes mellitus (DM) is a chronic metabolic condition marked by hyperglycemia caused by abnormalities in insulin production, action, or both." (PMID 36188225, 2022). "Hypoglycemia is an emergent condition with many causes, including underlying diabetes mellitus either with the use of insulin or oral anti-diabetic medications for glucose control, and organ (heart, hepatic, or renal) failure." (PMID 35758364, 2022). "Chronic hyperglycemia is a complication of diabetes mellitus, which is primarily caused by a deficiency in insulin production and/or insulin action induced by the failure of islet β-cells of Langerhans and insulin resistance." (PMID 35268685, 2022). "Recent studies suggest an increased insulin secretion capacity of β-cells with ZnT8 loss-of-function to be the reason for a lower risk to develop diabetes." (PMID 35017316, 2022). "Future work should investigate the dual roles of insulin and its receptor in other cancer types associated with obesity, diabetes mellitus or high insulin states." (PMID 34554347, 2022). "Diabetes mellitus is a metabolic disease characterized as hyperglycemia caused by deficient insulin secretion or impaired insulin effect." (PMID 35030973, 2022). "Type 1 diabetes mellitus is a common chronic disease in which the human immune system constantly attacks and destroys β cells, leading to insufficient insulin supply or insulin resistance, further causing the rise of blood glucose levels." (PMID 36501537, 2022). "When these pancreatic β-cells are damaged, diabetes develops through glucose intolerance caused by insufficient insulin secretion." (PMID 36292936, 2022). "This shortage in insulin production is caused either by an autoimmune process that destroys the insulin-producing cells (diabetes mellitus type 1) or by occurring insulin resistance of the body cells (diabetes mellitus type 2)." (PMID 36078223, 2022). "Previous studies have demonstrated that microcirculation dysfunction is related to impaired tissue perfusion, which can increase the risk of diabetes by impairing insulin-mediated changes in muscle perfusion and glucose metabolism." (PMID 36536445, 2022). "Although this is not annotated in STRING gene ontology, the revised literature reports that all of them are related to fasting insulin and show a significant association with diabetes and GDM." (PMID 36313769, 2022). "Insulin balls, localized insulin amyloids formed at the site of repeated insulin injections in patients with diabetes, cause poor glycemic control and cytotoxicity." (PMID 35595809, 2022). "Diabetes mellitus is caused by chronic high glucose levels in the blood as a result of the incapability of β cells in the pancreas to produce adequate insulin or ineffective insulin utilization by cells in the body." (PMID 35327468, 2022). "The use of these agents has been demonstrated to reduce 70% in the daily insulin doses often associated with better glycemic control in patients with diabetes by WS." (PMID 35270448, 2022). "Regarding comorbidities and risk factors for arteriosclerosis, 87.9% of patients had diabetes mellitus (DM), with 41.4% being insulin users." (PMID 35574536, 2022). "Diabetes is a heterogeneous endocrine and metabolic illnesses characterised via hyperglycemia due to deficiency or diminished effectiveness of insulin action, insulin secretion or both." (PMID 35620596, 2022).
diabetes (continued). "Diabetes mellitus (DM) is a group of metabolic disorders with insulin secretion deficiency, impaired insulin action, or both resulting in hyperglycemia." (PMID 36289886, 2022). "Diabetes is described as hyperglycemia caused by either insufficient insulin secretion due to autoimmune destruction of pancreatic β cells or insulin resistance." (PMID 35368463, 2022). "Diabetes mellitus (DM) is a state of hyperglycemia associated with metabolic disease due to impaired insulin release and/or function." (PMID 36060470, 2022). "The assessment of insulin sensitivity and secretion is vital for the early identification of people at risk of developing diabetes as well as for implementing interventions to prevent or delay the pathological progression of the disease." (PMID 35631177, 2022). "Small intervention studies have shown increased insulin secretion with supplementation with VitD3 in four subjects with insulin deficiency or with 1-alfa-OH-D3 in seven subjects with diabetes." (PMID 36014761, 2022). "Type-1 diabetes mellitus causes autoimmune damages responsible for insulin production, especially beta cells in the pancreas." (PMID 35197753, 2022). "In few cases, glucose homeostasis derangement can be significant, increasing the risk of DKA and requiring prompt insulin therapy, but in most cases it unlikely progresses to overt diabetes or requires substantial modification of OAD." (PMID 35744057, 2022). "T1DM is differentiated from T2DM in that it is an autoimmune disease, meaning the body destroys its own β cells; but the result is the same loss of insulin production leading to high blood glucose levels, or hyperglycaemia, and eventually diabetes." (PMID 36128718, 2022). "In contrast, the matched control group with complete insulin deficiency and solely insulin therapy resulted in item-scores between 1,0 and 1,9 (moderate diabetes-associated distress) only in the categories’social burden’ and ‘physician related burden’." (PMID 35603294, 2022). "It should also be noted that in stratified analyses, sacubitril/valsartan was associated with significantly higher risk for hypoglycemic adverse events only in patients with diabetes who used either insulin or sulfonylurea at baseline." (PMID 35717169, 2022). "Alloxan has been broadly employed by researchers to induce experimental diabetes in rodents, as it inhibits glucose-stimulated insulin secretion and causes necrosis of insulin producing cells of the pancreas." (PMID 36387342, 2022). "Cost-related insulin rationing occurs in 1 in 4 people with diabetes and has been associated with detrimental impacts on glycemic outcomes." (PMID 35436214, 2022). "Diabetes mellitus is a chronic disease in which there are disturbances in carbohydrate metabolism, due to deficiency in pancreatic insulin production and secretion, in type 1 diabetes (T1D), or its peripheral action, type 2 diabetes." (PMID 35758833, 2022). "Insulin alterations should also be considered, as this hormone plays an important role in the Fas pathway and has been linked to insulin resistance and diabetes." (PMID 36289594, 2022). "In fact, remission of T2D can be achieved after a >15% weight loss in most patients with short-term diabetes, partly associated with the recovery of first-phase insulin secretion, traditionally believed to be irreversibly lost in long-lasting T2D." (PMID 36061897, 2022). "Insulin resistance is also an important pathogenic factor with respect to diabetes mellitus, which is caused by the low sensitivity of peripheral tissue to insulin." (PMID 36140883, 2022). "Our findings demonstrated that salivary CRP and insulin were associated with hyperglycemia, obesity, and possibly diabetes in adolescents." (PMID 35757631, 2022). "The Diabetes Control and Complications Trial observed that low adherence to a healthy eating regimen was associated with a poorer glycemic control and higher insulin dose in adults and youths with type 1 diabetes." (PMID 35459205, 2022).
diabetes (continued). "Previous studies have associated diabetes (both type-1 and type-2) with AD, implicating hyperglycemia and abnormal insulin signaling in AD." (PMID 36175825, 2022). "On the other hand, inducible overexpression of Smad7 in adult mice causes overt diabetes with hypoinsulinemia, impaired glucose tolerance, and reduced pancreatic insulin content." (PMID 35327565, 2022). "In the multivariable descriptive models, male gender, diabetes duration, hypertension, macrovascular, microvascular complications, and insulin and antiplatelet agents were strongly associated with DFD." (PMID 36353236, 2022). "Diabetes in Asian is characterized by early β-cell dysfunction and develops at a younger age, requiring early insulin treatment and posing a higher risk of cardiovascular complications than that in Westerners." (PMID 36474232, 2022). "Diabetes is a metabolic disorder caused by insufficient insulin secretion and/or insulin resistance in target tissue." (PMID 35418946, 2022). "QSM associations with diabetes include formal diagnosis, self-report and relevant medication (insulin and metformin)." (PMID 35606419, 2022). "Insulin is recommended as first line of treatment for GDM by the American Diabetes Association (ADA)." (PMID 35195193, 2022). "HO-1 is induced by oxidant stress and plays a crucial role of antioxidant in diabetes by improving insulin sensitivity, reduces adipose tissue volume, and causes adipose tissue remodeling." (PMID 36684957, 2022). "Ketoacidosis is a complication of diabetes, which is mainly due to severe metabolic disorder syndrome caused by insufficient insulin secretion and excessive hormone secretion which antagonizes insulin." (PMID 36290938, 2022). "T2D accounts for approximately 90–95% of all diabetes cases and results from the gradual loss of adequate beta cell insulin secretion, frequently on the background of peripheral insulin resistance." (PMID 35629988, 2022). "Diabetes mellitus is one of the most prevalent metabolic syndromes caused due to deficits in insulin secretion and/or insulin resistance." (PMID 36295897, 2022). "While this mechanism was ignored for decades, insulin degradation is now being recognized as a possible factor in diabetes risk." (PMID 35163746, 2022). "The expression of such a combination of transcription factors is beneficial and efficient for replacing the reduced insulin biosynthesis associated with diabetes and treating the disease." (PMID 36551213, 2022). "The reported literature has proved that oxidative stress can cause cardiovascular disease, diabetic nephropathy, and insulin dysfunction in the host, increasing the risk of developing diabetes." (PMID 35845787, 2022). "Diabetes mellitus (DM) is a chronic metabolic disease, which is caused by the lack or ineffective use of insulin produced by the body." (PMID 35062385, 2022). "MODY is characterized by autosomal dominant inheritance, early onset of diabetes under 25 years of age, and impaired insulin secretion due to mutations in transcription factors involved in beta cell differentiation and function." (PMID 35328643, 2022). "Currently, pharmacological therapies such as insulin and metformin are primarily used to treat diabetes, but these therapies significantly raise the risk of cardiovascular disease and all-cause mortality." (PMID 36364943, 2022). "Chronic insulin therapy reverses the catabolic weight loss of poorly controlled diabetes and beyond this, often induces undesirable weight gain, aggravating risk of obesity." (PMID 35177603, 2022). "Mutations in KCNJ11 inhibit the ability of ATP to regulate the potassium channel while enhancing stimulatory magnesium, altering insulin secretion and ultimately causing diabetes." (PMID 36128718, 2022). "Knowing that patients with type 1 diabetes mellitus have insulin deficiency, there is an immediate need for exogenous insulin replacement." (PMID 36384715, 2022).
diabetes (continued). "Specifically, the N221D allele has a strong tie to diabetes due to its deleterious effect on insulin sensitivity and oral glucose tolerance, while increasing the circulating proinsulin." (PMID 36012526, 2022). "Lower adipose tissue ACE2 expression was associated with diabetes and obesity status, increased serum fasting insulin and triglyceride levels, BMI, and with increased macrophage infiltration in adipose tissue, a marker of inflammation." (PMID 35589964, 2022). "Hyperglycemia and oxidative stress are two important factors in the development of diabetes and are associated with altered expression levels of insulin gene-stimulating transcription factors." (PMID 36109786, 2022). "Research in rats showed early stage memory formation deficits caused by diabetes can be successfully prevented by insulin treatment." (PMID 36232867, 2022). "Low-carbohydrate diets, which have recently attracted much attention, are effective in weight loss and the prevention of chronic diseases such as diabetes by regulating the glucose–insulin axis." (PMID 35407137, 2022). "Diabetes mellitus (DM) is an endocrine and metabolic disease caused by increased blood glucose levels due to insufficient insulin secretion or increased insulin resistance." (PMID 35692502, 2022). "Type-2 diabetes mellitus (T2DM) is the most common type of metabolic disorder caused by abnormal regulation of insulin." (PMID 36497027, 2022). "Diabetes mellitus (DM) is a metabolic syndrome associated with hyperglycemia due to the body's inability to produce sufficient amount of insulin or abnormalities in its secretion or tissue resistance to its action." (PMID 35096118, 2022). "Patients with type 2 diabetes treated with insulin showed a 20% excess risk for all cancer sites compared with both the general population and with patients with diabetes on diet-only treatment." (PMID 35681699, 2022). "Diabetes mellitus is caused by increased blood glucose levels (hyperglycemia) due to defects in insulin action, insulin secretion, or both." (PMID 35631811, 2022). "The insulin signaling pathway controls cell growth and metabolism, thus its deregulation is associated with both cancer and diabetes." (PMID 35678366, 2022). "As a matter of fact, while insulin amyloidosis is rarely encountered in mammals, several insulin-derived amyloidoses at the injection site have been associated with diabetes mellitus." (PMID 35330199, 2022). "Based on the multivariate Cox model, COVID-19 patients with diabetes treated with oral medication only or with oral medication plus insulin had a significant lower mortality risk than those treated with insulin only." (PMID 35047039, 2022). "PF via FMD has also been demonstrated to modulate functional β-cell mass in insulin-deficient and HF diet models of diabetes; however, the ability to translate these findings are confounded by the limited replicative capacity of human β-cells." (PMID 35355560, 2022). "Elevated urea levels during diabetes cause diabetic nephropathy associated with impaired insulin level, protein catabolism, and oxidative damage, leading to nephrotic damage." (PMID 36304231, 2022). "Another cross-sectional study carried out in Qassim, Saudi Arabia in 2020 on 374 patients with diabetes showed that a multi-drug approach and insulin use, in particular, was associated with a high risk of developing DN." (PMID 36348847, 2022). "Diabetes is a metabolic disorder characterized by chronic hyperglycemia caused by impaired insulin secretion or impaired insulin action or both." (PMID 36364821, 2022). "The mechanism underlying IR as a risk factor for ASCVD relates to the reduced ability of insulin to take up and utilize glucose, which leads to diabetes and is a major intermediate in ASCVD progression." (PMID 36351977, 2022). "For example, disturbed rhythmic insulin secretion from the pancreas predisposes mammals to diabetes." (PMID 35204721, 2022).